MED13 (mediator complex subunit 13)
Description:
Component of the Mediator complex, a coactivator involved in the regulated transcription of nearly all RNA polymerase II-dependent genes. Mediator functions as a bridge to convey information from gene-specific regulatory proteins to the basal RNA polymerase II transcription machinery. Mediator is recruited to promoters by direct interactions with regulatory proteins and serves as a scaffold for the assembly of a functional preinitiation complex with RNA polymerase II and the general transcription factors.
Synonyms: ARC250; Trap240; DRIP250; KIAA0593; THRAP1; HSPC221; MRD61
Tractability: PROTAC: ubiquitination databases record sites on it.
Gene: Protein-coding gene on chromosome 17 (61,942,605 to 62,065,278, reverse strand). Ensembl gene ENSG00000108510.
Subcellular location: Nucleus
Subcellular location (Human Protein Atlas): Nucleoplasm
Pathways (Reactome):
Gene expression (Transcription): Generic Transcription Pathway; MLL4 and MLL3 complexes regulate expression of PPARG target genes in adipogenesis and hepatic steatosis
Developmental Biology: Transcriptional regulation of white adipocyte differentiation
Disease: RSV-host interactions
Metabolism: PPARA activates gene expression
Gene Ontology:
Molecular function: nuclear thyroid hormone receptor binding; protein binding; transcription coactivator activity; transcription coregulator activity; nuclear vitamin D receptor binding
Biological process: positive regulation of DNA-templated transcription; positive regulation of transcription by RNA polymerase II; positive regulation of transcription initiation by RNA polymerase II; cholesterol homeostasis; negative regulation of transcription by RNA polymerase II; regulation of transcription by RNA polymerase II; triglyceride homeostasis
Cellular component: CKM complex; mediator complex; membrane; nucleoplasm; nucleus
Genetic constraint (gnomAD): Loss-of-function variants: 17 observed, 195.57 expected, observed/expected ratio (o/e) 0.0869, 90% interval 0.058 to 0.13. The upper end of that interval is the gene's LOEUF score, 0.13, which puts it in group 1 of 6, group 1 being the genes least tolerant of losing a copy. Missense variants: 2,077 observed, 2,535.5 expected, observed/expected ratio (o/e) 0.82, 90% interval 0.79 to 0.85. Synonymous variants: 885 observed, 880.99 expected, observed/expected ratio (o/e) 1, 90% interval 0.95 to 1.06.
Gene-disease validity (ClinGen):
ClinGen rates the evidence that MED13 causes each of these diseases.
complex neurodevelopmental disorder (autosomal dominant): Definitive. A disorder that involves more than one phenotype associated with the central nervous system, including but not limited to intellectual disability, autism, and seizures (epilepsy).
Homologues: Orthologues: chimpanzee MED13 (99% identical), macaque MED13 (99% identical), rabbit MED13 (95% identical), pig MED13 (94% identical), mouse Med13 (94% identical), rat Med13 (94% identical), guinea pig MED13 (92% identical), tropical clawed frog med13 (80% identical), zebrafish med13a (70% identical), zebrafish med13b (65% identical), Drosophila melanogaster skd (33% identical), Caenorhabditis elegans let-19 (25% identical). Paralogues in human: MED13L (54% identical).
Diseases named in the same sentence as MED13 in open-access papers:
MED13 is named in the same sentence as 52 diseases in open-access papers, as found by Europe PMC text mining. Sharing a sentence is not in itself a finding about the gene and the disease. The quoted sentences say what the papers report.
Obesity (14 papers, 2014 to 2025). Accumulation of substantial excess body fat. "The knockout of MED13 in mouse hearts significantly enhanced susceptibility to obesity, indicating a crucial role of the heart MED13/nuclear receptor signaling in obesity." (PMID 40940746, 2025). "Previous study reported that MED13 overexpression enhanced lipid metabolism, insulin sensitivity, and decreased susceptibility to obesity." (PMID 36685918, 2022). "Cardiac MED13 is involved in systemic energy metabolism, and is associated with obesity, diabetes, and other diseases linked to energy metabolism." (PMID 33390853, 2021). "In contrast, cardiac-specific deletion of MED13 increases obesity upon high-fat diet and susceptibility to metabolic syndrome." (PMID 30693281, 2018). "The opposite finding, i.e. susceptibility to obesity, was observed in the condition of myocardial MED13-deletion." (PMID 24932507, 2014). "Besides, the knockdown of MED13 increases susceptibility to obesity by regulating Wingless in Drosophila." (PMID 34460892, 2021). "Moreover, deletion of cardiac KLF5 results in susceptibility to diet-induced obesity in mice, which can be suppressed by expression of cardiac MED13." (PMID 33390853, 2021). "In addition, cardiac-specific ablation of MED13 increases susceptibility to obesity, while cardiac overexpression of MED13 leads to a lean phenotype, which shows the crucial role of MED13 in obesity." (PMID 37667400, 2023). "In addition, muscle-specific knockdown of MED13 in mice increases their susceptibility to obesity." (PMID 33390853, 2021). "MED13 participates in pathological adipocyte hypertrophy, and lower MED13 level has been observed in obesity and diabetes." (PMID 37667400, 2023). "Its expression increases with adipocyte hypertrophy and obesity, and it plays a role in adipose regulation by inhibiting MED13 expression." (PMID 37667400, 2023). "MED12 and MED13 have similar functions in controlling obesity in Drosophila, especially heart and muscle MED12 and MED13." (PMID 33390853, 2021). "Conversely, upregulating MED13 expression confers resistance to obesity in animal models upon pharmacologic miR-208a inhibition or rapamycin treatment." (PMID 33390853, 2021). "Transgenic expression of Med13, a target of miR-208a, in cardiac muscle attenuated the metabolic defects in mouse models of obesity, phenocopying the effects of miR-208a inhibition." (PMID 34957257, 2021). "Intriguingly, Med13 has been found to inhibit lipid accumulation in Drosophila, thus the anti-obesity function appears to be conserved in invertebrates." (PMID 34957257, 2021). "Deletion of MED13 in mouse cardiomyocytes enhanced obesity in response to a high-fat diet and exacerbated metabolic syndrome due to the inhibition of a cardiomyocyte secretory factor." (PMID 33812059, 2021). "Knockdown of cardiac MED12 and MED13 in Drosophila increases fat accumulation and induces obesity, which suggests that like MED13, cardiac MED12 also can control metabolism homeostasis." (PMID 33390853, 2021). "Overexpression of MED13 in cardiomyocytes protected mice from high-fat diet-induced obesity and improved glucose tolerance and insulin sensitivity." (PMID 30693281, 2018). "Specifically, myocardial overexpression of MED13 (or inhibition of its regulatory microRNA, miR-208a) led to resistance to obesity and systemic insulin-resistance when challenged with high-fat feeding." (PMID 24932507, 2014). "MED13 transgenic mice show reduced expression of metabolic genes in the heart, whereas metabolic activity increases in the adipose tissue and liver to counteract obesity development." (PMID 37150323, 2023). "A further study indicates that both rapamycin and nebivolol may suppresses the up-regulation of miR-208a via inhibiting mTORC1 activation, thus increasing the level of MED13 and conferring the resistance of obesity." (PMID 34957257, 2021).
Obesity (continued). "Pharmacological interventions to modulate cardiac miR-208a-MED13 signaling or MED13-regulatedcardiokines may provide therapeutically useful avenues in obesity, diabetes, dyslipidemia, and theother systemic metabolic disorders." (PMID 25471454, 2014). "Transgenic mice with enhanced cardiac MED13 expression (MED13cTg mice) display a lean phenotype,have a 15% reduction in fat mass at 12 weeks of age on normal chow compared to WTmice, and are resistant to diet-induced obesity." (PMID 25422356, 2014). "Might endogenouscardiac MED13 signaling be regulated in response to metabolic stress, such as obesity and insulinresistance?" (PMID 25471454, 2014). "Therefore, targeting MED13 and its upstream regulators might be beneficial for inhibiting pathological adipocyte hypertrophy in obesity and diabetes." (PMID 37667400, 2023). "Thus, MED13 is an important link between cardiac physiology, insulin resistance and obesity." (PMID 29259233, 2017). "Cardiac overexpression of MED13 in transgenic (α-myosin heavy chain [αMHC]-MED13-TG or MED13-cTG) mice promotes sensitivity to insulin and increases energy expenditure, thereby preventing high-fat diet (HFD)-induced obesity." (PMID 33390853, 2021). "The study demonstrated that miR-208a/Med13 axis in cardiac muscle was involved in regulating the energy homeostasis in distant organs, including fat tissue and liver, and indicated that miR-208a could be a promising therapeutic target for metabolic disorders such as type 2 diabetes and obesity." (PMID 34957257, 2021). "Furthermore, miRNA-208a downregulates MED13 by binding with the MED13 mRNA 3′UTR in obesity and diabetes." (PMID 37667400, 2023). "Adipocyte proliferation, which is also named adipogenesis, is predominant in the pathological process of obesity and obesity-related diseases, and MED13 levels are negatively correlated with adipocyte proliferation in HFD-induced obesity." (PMID 37667400, 2023). "Interestingly, cardiac-specific overexpression of MED13, a subunit of the mediator complex involved in nuclear hormone receptor–mediated gene transcription, protects mice from HFD-induced obesity and insulin resistance." (PMID 37150323, 2023).
cardiac hypertrophy (9 papers, 2013 to 2025). "MED13 is a target of miR-208a, a microRNA that promotes cardiac hypertrophy and heart failure." (PMID 29259233, 2017). "Heart-specific transgenic overexpression of miR-208a resulted in cardiac hypertrophy and suppression of both MED13 and myostatin 2 that negatively regulate muscle growth and hypertrophy and induced arrhythmias in mice." (PMID 36909327, 2023).
Intellectual disability (7 papers, 2018 to 2025). "For instance, we showed that ENO1 and ALDOA interact with MED13, which has been associated with a broad range of NDDs including encephalopathy, intellectual disability, and autism." (PMID 37664457, 2023). "Genetic alterations leading to a truncated version of MED13 or Med13 harboring missense mutations have been found in humans with intellectual disability and/or developmental- and speech delays." (PMID 30693281, 2018). "TGex analysis (LifeMap Sciences, USA) prioritized 9 candidate variants across 7 genes (MED13, POGZ, SETBP1, SCN9A, SCO1, APTX, TIE1) associated with phenotypes including congenital megacolon, intellectual disability, motor delay, and developmental delays." (PMID 41195223, 2025). "Recently, de novo variants in the Mediator complex subunit 13 (MED13, OMIM 603,808) were detected in a cohort of 13 patients with intellectual disability and dysmorphisms." (PMID 38745205, 2024).
autism (4 papers, 2020 to 2025). Persistent deficits in social interaction and communication and interaction as well as a markedly restricted repertoire of activity and interest as well as repetitive patterns of behavior. "The MED13 variant was initially detected through whole exome sequencing (WES) in a large group of patients with autism, for whom a detailed clinical description was unavailable." (PMID 41195223, 2025). "We found differential expression of autism-relevant genes in our DE gene list that are also associated with cell adhesion (Dscam, Reln) or gene regulation (Kat2b, Kmt2c, Med13/Med13l, Tbl1xr1, Ubn2)." (PMID 33757588, 2021). "MED13 is related to development, and its mutation can cause autism." (PMID 32273901, 2020). "This indicates that MED13 affects development through P6 and then induces autism." (PMID 32273901, 2020). "From the single gene annotation analysis, it can be seen that the abnormalities of MED13, POU3F2, and USP8 have been confirmed to induce autism." (PMID 32273901, 2020).
developmental delay (4 papers, 2022 to 2025). "Recently, de novo variants in the MED13 gene were described in patients with an intellectual developmental disorder that included global developmental delay, mild congenital heart anomalies, and hearing and vision problems in some patients." (PMID 38745205, 2024). "MED13L patients show developmental delay and ID and many of the phenotypes also observed for MED13 and MED12 variants, such as ASD and hypotonia." (PMID 35615272, 2022). "MED13 variants were subsequently described in patients with ASD and, recently, missense or truncating variants were identified in thirteen patients presenting with developmental delay, ID, and speech disorders." (PMID 35615272, 2022).
hypothyroidism (3 papers, 2014 to 2021). Abnormally low levels of thyroid hormone. "Moreover, in the context of hypothyroidism, deletion of cardiac MED13 exacerbates cardiac dysfunction." (PMID 33390853, 2021). "The expressions of myh7 and Serca2a genes are lower in cardiac MED13 knockout (MED13-cKO) mice than wild-type mice 82, suggesting that cardiac MED13 plays a role in cardiac function conservation in hypothyroidism, as myh7 and Serca2a expressions are necessary to maintain normal cardiac function." (PMID 33390853, 2021). "The expression cardiac MED13 is increased in response to hypothyroidism and the increased MED13 expression might repress cardiac pro-inflammatory and pro-fibrotic gene transcriptions 82, which may be a potential mechanism for MED13 modulating cardiac transcription in the context of hypothyroidism." (PMID 33390853, 2021). "Therefore, in response to hypothyroidism, there would be prediction that overexpression of miR-208a inhibits MED13 and additional targets expression, thereby enhancing β-MHC expression via reducing the repressive activity of TRs towards β-MHC and altering cardiac function." (PMID 33390853, 2021).
diabetes (2 papers, 2017 to 2023). "Importantly, reduction in cardiac Med13 in response to T2DM in both sexes was similar, indicating its role in promoting cardiac insulin resistance in diabetes." (PMID 29259233, 2017).
Hepatic steatosis (2 papers, 2021). Steatosis is a term used to denote lipid accumulation within hepatocytes. "In contrast, MED13 deficiency in skeletal muscle increased insulin sensitivity and protected mice against high-fat diet-induced hepatic steatosis." (PMID 33812059, 2021).
metabolic syndrome (2 papers, 2021). A cluster of metabolic risk factors for CARDIOVASCULAR DISEASES and TYPE 2 DIABETES MELLITUS. "MED13 is also associated with several pathological conditions, such as metabolic syndrome and thyroid disease-associated heart failure." (PMID 33390853, 2021). "MED13 plays critical roles in diseases like metabolic syndrome and cardiovascular disease." (PMID 33390853, 2021).
Asperger’s syndrome (1 paper, 2023). "Patient AUT118, who has a variant in the MED13 gene, has been presumptively diagnosed with Asperger’s syndrome, but we classified the variant as VUS." (PMID 38003033, 2023).
autism spectrum disorder (1 paper, 2024). A spectrum of developmental disorders that includes autism, and Asperger syndrome. "This case report highlights an association between the MED13 gene and autism spectrum disorder (ASD)." (PMID 38854223, 2024).
breast carcinoma (1 paper, 2016). "Taken together, we found 13 previously known high-risk gene fusions of breast cancer such as BCAS3-BCAS4, NOTCH- NUP214, MED13- BCAS3 and CARM-SMARCA4, and 8 potential drivers such as SULF2-ZNF217, MED1-ACSF2." (PMID 27506935, 2016).
clear cell renal cell carcinoma (1 paper, 2022). "In the clear cell renal cell carcinoma cohort, the DST, MED13 and ABCC6 gene mutation frequencies significantly differed among different low and high IP-score groups." (PMID 36700205, 2022).
colon cancer (1 paper, 2020). "On the contrary, in colon cancer, simultaneous depletion of MED13L and MED13 led to decreased cell viability 36 and supported the oncogenic functions of MED13L, which is consistent to our findings in NSCLC." (PMID 32802198, 2020).
colorectal cancer (1 paper, 2012). A primary or metastatic malignant neoplasm that affects the colon or rectum. "Interestingly, among intrinsic growth gene eQTLs, we found two well replicated colorectal cancer SNPs (rs4779584 and rs3802842), which target growth-associated genes NEU1 and MED13; both genes have been implicated in colorectal cancer." (PMID 22346769, 2012).
deafness (1 paper, 2024). An inherited or acquired condition characterized by the complete loss of the ability to hear from one or both ears. "The patients carrying MED13 variants are also suffering neurodevelopmental disorders that are in many cases accompanied by heart anomalies, motor delay, dysmorphic features, microcephaly, deafness, retinal dystrophy and corpus callosum abnormalities." (PMID 38745205, 2024).
diabetic cardiomyopathy (1 paper, 2018). Diabetic cardiomyopathy is a disorder of the heart muscle in people with diabetes. "Developing drugs that can increase expression of MED13 and AT2R in diabetic heart can lead to better treatment paradigms for diabetic cardiomyopathy and to mitigate sex differences in this pathology." (PMID 29773993, 2018).
epilepsy (1 paper, 2024). A brain disorder characterized by episodes of abnormally increased neuronal discharge resulting in transient episodes of sensory or motor neurological dysfunction, or psychic dysfunction. "The clinical presentations of individuals with pathogenic MED13 variants include variable combinations of NDD, dysmorphic features, and epilepsy among others." (PMID 38300321, 2024).
glioblastoma (1 paper, 2021). The most malignant astrocytic tumor (WHO grade IV). "To examine the importance of MED13 in modulation of alkylation response beyond HAP1 cells, we next inactivated MED13 by CRISPR–Cas9 in glioblastoma G144 cells and generated two independent MED13 KO cell lines (MED13 KO cl.5 and cl.12)." (PMID 33444446, 2021). "Importantly, the immunoblot analysis showed that treatment with Senexin A significantly stabilizes MED13 protein levels, and that this effect is maintained upon the combinatory treatment with MMS in HAP1 cells, as well as HeLa adenocarcinoma and T98G glioblastoma cells." (PMID 33444446, 2021).
Hip dysplasia (1 paper, 2021). The presence of developmental dysplasia of the hip. "Furthermore, it was previously reported that hip dysplasia was one of the clinical features of a human patient with MED13 mutations." (PMID 34474664, 2021). "MED13 (Chr 9) and PLEKHA7 (Chr 21) emerged as novel positional candidate genes associated with hip dysplasia." (PMID 34474664, 2021).
hypertrophic cardiomyopathy (1 paper, 2025). A condition in which the myocardium is hypertrophied without an obvious cause. "Here we report a de novo heterozygous MED13 variant (c.2503C>T, p.Pro835Ser) in an infant presenting with infantile spasms, hypertrophic cardiomyopathy and hepatomegaly." (PMID 41130977, 2025).
idiopathic scoliosis (1 paper, 2012). A scoliosis with no known cause. "In paravertebral muscles Tob2 and Med13 genes differentiate Adolescent and Juvenile type of Idiopathic Scoliosis." (PMID 23259508, 2012).
intellectual developmental disorder 61 (1 paper, 2023). "On the other hand, the MED13 gene has been associated with intellectual developmental disorder 61 (OMIM #618009)." (PMID 38003033, 2023).
leiomyoma (1 paper, 2020). A well-circumscribed benign smooth muscle neoplasm characterized by the presence of spindle cells with cigar-shaped nuclei, interlacing fascicles, and a whorled pattern. "This aligns with recently published data in heterologous cell lines as well as leiomyoma tissue samples, which demonstrate that the presence of MED13 is a stabilizing protein in the submodule that compensates for any MED12 mutant-dependent interaction defect." (PMID 32094355, 2020).